EPCAM (epithelial cell adhesion molecule)
Diseases named in the same sentence as EPCAM in open-access papers (continued):
Sharing a sentence is not in itself a finding about the gene and the disease.
cancer (continued). "Microarray analyses of primary PCA cells derived from these models identified several cancer stemness genes including CD24, EpCAM, and CD133 upregulated by KRASG12D." (PMID 30467381, 2019). "We quantified by an ELISA-based technique specific proteins of cancer-derived exosomes (CD44,CD44v6,EpCAM,CD9,CD81,Tspan8,Integrin α6,Integrin β4,CD24,CXCR4)." (PMID 31048929, 2019). "Coexpression of cancer-related markers, such as cytokeratins or EpCAM, and hematopoietic lineage markers, such as CD45 and CD163, is another strategy to identify putative TN-hybrid cells in human cancers." (PMID 30736482, 2019). "We compared an EpCAM-based positive isolation method and a CD45/CD66b-based negative isolation method, using MDA-MB-231, PC-3, SKBR-3, and MCF-7 cancer cells, which have different surface expression levels of EpCAM." (PMID 31181790, 2019). "Several CSC marker molecules, such as CD166, epithelial cell adhesion molecule (EpCAM) and CD44, have been identified and have become useful markers in human cancers." (PMID 30788285, 2019). "Our data are in agreement with recent data showing the presence of atypical CTCs, characterized by the expression of EPCAM, pan-CK, and CD45, in several cancer types." (PMID 31552188, 2019). "Many surface markers of CSCs have been used as target antigens for immunotherapy in cancer treatment, such as CD133, CD90, ALDH, and EpCAM, and revealed encouraging anticancer activity." (PMID 31288857, 2019). "EpCAM and vimentin expression levels of biological replicates from the mixture of NCI-N87 cancer cells with fibroblasts at different ratios showed significant correlations with minimal variations." (PMID 31850215, 2019). "However, it is not clear whether our previously reported large tdEVs are a result of the fragmentation of CTCs during the immunomagnetic EpCAM enrichment and washing steps that the CellSearch system is using or whether they pre-exist in the blood samples of cancer patients." (PMID 31434250, 2019). "However, cancer research continues to reveal new classes of biologically relevant CTCs with high phenotypic variability and physical heterogeneous features, such as circulating cancer cell hybrids incorporating both hematopoietic and epithelial properties (EpCAM-positive, CD45-positive)." (PMID 31146464, 2019). "KrasG12D/p53loss induces cancer stem cell traits, with increased CD24, EpCAM, and CD133 expression as seen in advanced metastatic PCA." (PMID 30467381, 2019). "Due to its high incidence in tumors, EpCAM has been one of the CSC targets in clinical studies, and specific anti-EpCAM antibodies have been tested in cancer patients." (PMID 31547062, 2019). "Hepatocytic (HNF4), EMT (Twist, Snail), and cancer stem cell markers (CD44, EpCAM, CK19, Sox9) were simultaneously expressed in these cells." (PMID 31726709, 2019). "In light of the obvious connection between EpCAM expression and distant metastasis in clinical samples, we examined the potential regulation of EpCAM on EMT, which is considered to be a critical process in cancer metastasis." (PMID 29305578, 2018). "qPCR analysis showed increased expression of many CSC marker genes such as ALDH1, ABCG2, NESTIN, EpCam and CD90, altogether suggesting that hTERT plays a significant role in the expression of cancer and CSC markers." (PMID 29907642, 2018). "EpCAM (also known as ESA or CD326) has been shown to be oncogenic and found in CSCs as well as cancer exosomes." (PMID 29415026, 2018). "We also found that the expression pattern of EpCAM is closely related to the status of EMT and the invasion property of the cancer cells." (PMID 30547810, 2018). "Cell type-specific Exo proteins are so far most comprehensively explored for cancer and cancer stem cells (CSC), such as MART1, EGFRVIII, multidrug resistance gene 1, EpCAM, MET, mutant KRAS, and tissue factor." (PMID 29456536, 2018).
cancer (continued). "Ectopic EpCAM expression in NPC cells promoted epithelial-mesenchymal transition (EMT), induced a cancer stem cell (CSC)-like phenotype, and enhanced metastasis in vitro and in vivo without an effect on cell proliferation." (PMID 29305578, 2018). "Cancer stem cells from NSCLC lines (A549 and H2170) were isolated based on expression of surface markers CD166, CD44, and EpCAM." (PMID 29868483, 2018). "Ultimately, insight into EpCAM’s protein interactions can drive a deeper understanding of EpCAM in various contexts ranging from diseases such as CTE and cancer to developmental processes." (PMID 30304739, 2018). "Epithelial cell adhesion molecule EpCAM is expressed in pluripotent embryonic stem cells (ESC) in vitro, but is repressed in differentiated cells, except epithelia and carcinomas." (PMID 29379062, 2018). "Epithelial cell adhesion molecule (EpCAM), also known as CD326, is a transmembrane glycoprotein that is highly expressed in rapidly proliferating carcinomas." (PMID 30419852, 2018). "Correspondingly, the epithelial phenotype with high CDH1 expression, low expression of VIM and low expression of EMT-inducing transcription factors correlates with high expression of cancer stem cell markers CD133 and EPCAM." (PMID 29299154, 2017). "CD133+ cell samples also showed higher expression of another cancer stem cell gene, BMP7, compared to CD133−/EpCAM+ cell samples (p = 0.0081)." (PMID 28347289, 2017). "Because CSCs exhibit increased aggressiveness, aggressive cancer cells are most commonly identified and sorted by flow cytometry using combinations of CSC cell-surface markers such as CD44, CD133 and EpCAM." (PMID 29156833, 2017). "mRNA and protein levels of the tumourigenic cancer stem cell markers CD24, CD133, EpCAM, and β-catenin were higher in the spheroids cultured with HUVECs." (PMID 28874716, 2017). "This review will focus on commonly expressed antigens on solid tumors, such as EpCAM, HER family, CEA, and PSMA, and BsAB targeting these antigens are also extensively investigated and have demonstrated a great potential in cancer immunotherapy." (PMID 28931402, 2017). "Cancer cell recovery efficiency was estimated by on-filter staining with DAPI and epithelial- or leukocyte- specific antibodies for cytokeratin, EpCAM, and CD45, respectively." (PMID 28129357, 2017). "It promoted HCC-related gene expression and furthermore, increased the expression of cancer stem cell markers including CD133, EpCAM, and CD 24, with CD133 being the most abundant in the Huh7 spheroids." (PMID 28874716, 2017). "Several cancer stem cell markers (CD24, CD133, and EpCAM) were highly expressed in Huh7/2% HUVECs-3D." (PMID 28874716, 2017). "There are a variety of cell surface markers used to identify and enrich CSCs from different human cancers, such as CD44, CD24, CD29, CD133 and epithelial cell adhesion molecule (EpCAM)." (PMID 28969077, 2017). "We screened for cancer cells expressing at least one EMT marker, such as ACTA2, EPCAM, CD44, THY1, VIM, FN1, ZEB1 or CDH1." (PMID 29079795, 2017). "qPCR analysis showed increased expression of many cancer stem cell marker genes such as ALDH1, ABCG2, CD90, NESTIN, PTEN, and EpCam." (PMID 29115987, 2017). "EpCAM (CD326) is a Ca2+ independent adhesion molecule, generally expressed on the basolateral surface of epithelial and carcinoma cells in OSCC." (PMID 29285029, 2017). "All cell types were negative for haematopoietic cell markers CD45, CD34, CD19, CD14, human lymphocyte antigen-DR (HLA-DR), the carcinoma cell marker (c-MET) and EPCAM." (PMID 28419140, 2017). "In the present study, we provide additional evidence that decreased EpCAM expression is correlated with expression of EMT markers and cancer stem cell markers." (PMID 27013581, 2016). "In this paper, we engineered the TetraKE 1615EpCAM133 to simultaneously engage EpCAM and CD133 increasing its targeting capability to target cancer cells and CSC alike." (PMID 27650544, 2016).
cancer (continued). "We compared four methods of human cancer cell isolation: fluorescence-activated cell sorting (FACS), an immunomagnetic mouse cell depletion (MCD) approach, and two distinct EpCAM-based immunomagnetic positive selection methods." (PMID 27611664, 2016). "For example, catumaxomab, which targets both epithelial cell adhesion molecule (EpCAM) and cluster of differentiation 3 (CD3) has been approved for the treatment of patients with EpCAM-positive cancer in Europe19." (PMID 26841833, 2016). "Next cancer cell labeling with EpCAM beads was examined through static experiments (PANC‐1 cells and EpCAM beads in an Eppendorf tube) and on‐chip experiments (on‐chip passive mixing of cells and beads subsequently flowed into reservoirs)." (PMID 27711257, 2016). "The finding that the EGF‐like domain of EpCAM is cleaved off in cancer cells which have undergone EMT also provides new insights in research of EMT and CSC, two important fields in cancer biology." (PMID 26775583, 2016). "The two new cell lines exhibited CD44+/CD49f+ and CD44+/EpCAM+ cancer stem cell (CSC) characteristics, and the EGF‐like domain of EpCAM was cleaved off." (PMID 26775583, 2016). "Catumaxomab, a bispecific scFv antibody targeting EpCAM on tumor cells and CD3 on T-cells, showed efficacy in the clinical treatment of carcinoma related malignant ascites." (PMID 27240402, 2016). "Annexin A1 was exclusive to MCF-7 exosomes while EpCAM was exclusive to MDA-MB-231-derived exosomes and both contained Annexin A2 and α-enolase, the latter of which has been shown to promote cancer cell growth, migration, and metastasis." (PMID 26601108, 2015). "CD90, the epithelial cell adhesion molecule (EpCAM) and CD133 have been found to recognize three distinct cell populations that differ from one another in features and behavior in determining cancer phenotypes." (PMID 26272696, 2015). "Recent studies have identified several cancer stem-cell surface markers including CD133, CD44 and EpCAM, although global markers for CSCs in different human cancers are difficult to establish." (PMID 26506419, 2015). "Furthermore, because the CellSearch System detects and quantifies CTCs based on the EpCAM protein on the CTCs, some investigators consider that EpCAM might play an important role in hepatic metastasis, cancer stemness, and the epithelial mesenchymal transition." (PMID 25880692, 2015). "They express specific cell-surface markers such as CD133, CD44 and EpCAM; these markers can be used to isolate CSC population from primary tumors and established cancer cell lines." (PMID 26506419, 2015). "The first is direct induction of cancer cell apoptosis or inhibition of EpCAM cleavage into EpICD and EpEX by binding to positions Y95 and D96 of the EGF-II/TY domain on intact EpCAM." (PMID 26317650, 2015). "Due to the low expression of EPCAM and cytokeratin, it was much more difficult to separate the MDAMB231 cancer cell from blood than the other two cell lines." (PMID 28936247, 2015). "Increased expression of cancer stem cell (CSC) markers, including c-Met, CD133, CD44, EpCAM (also known as ESA), ALDH1, Nanog, Oct4 and SOX2, has been identified in PDA." (PMID 25846752, 2015). "EpCAM RNA aptamer functionalized with either doxorubicin or SPION-nucleolin aptamers, or bovine lactoferrin showed greater specificity for cancer cells." (PMID 25576037, 2015). "Class C carcinomas (CLC) are morphologically heterogeneous and comprise interconvertible EpCAM+CD133+ epithelial and EpCAM−CD133− mesenchymal cells." (PMID 26158412, 2015). "We find that co-treatment of colorectal mAbs (anti-epithelial cellular adhesion molecule (EpCAM), plant-derived monoclonal antibody (mAbP) CO17-1A and mAbP CO17-1A × BR55) with RAW264.7 cells significantly inhibited the cell growth in SW620 cancer cells." (PMID 25405740, 2014). "SUM159 cells formed tumorspheres in culture, and the cancer stem cell subpopulation, CD24−/EpCAM+ cells, was markedly enriched in SUM159 tumorspheres." (PMID 25229616, 2014).
cancer (continued). "EpCAM-decorated buoyant immune-microbubbles, for example, have been used to detect both spiked and endogenous cancer cells from whole blood, while cytokeratin has been tested as markers for CTC detection individually, or in combination with the EpCAM protein." (PMID 24551200, 2014). "Therefore, we thought that EpCAM could become a useful cancer stem cell marker in a HCC." (PMID 24696843, 2014). "It is reported that only a few cancer cells possess the abilities of cancer stem cells and express the surface markers such as CD133, CD90 and EpCAM." (PMID 23382894, 2013). "The cancer cells (PC-9 and MCF-7) were isolated from whole blood with EpCAM-microbeads and isolated fractions labeled with an antibody targeting a different EpCAM epitope, anti-CD45, Syto9 and PI dyes (live/dead staining)." (PMID 24305653, 2013). "Among all the human cancer cell lines studied here, MDA-MB-231 cells express the lowest amounts of EpCAM (1.7×103 binding sites/cell in MDA-MB-231 vs 222.1×103 binding sites/cell in MCF7." (PMID 23460885, 2013). "Cell adhesion molecules, such as epithelial cell adhesion molecule (EpCAM; CD326), play a pivotal role in the pathogenesis of cancer." (PMID 23320927, 2013). "Although the function of TROP2 is less defined than that of EpCAM, TROP2 has also been suggested as oncogene, promoting cancer cell proliferation and migration, and cell adhesion molecule." (PMID 22482828, 2012). "We investigated the expression of four markers that have previously been described for isolation of several types of human CSCs in human cancer cell lines: CD44, CD24, ABCG2, and EpCAM." (PMID 22328825, 2012). "Although the EpCAM and TROP2 proteins were discovered some time ago, only recently have they become the focus of research in various cancers." (PMID 22482828, 2012). "To investigate the efficiency of ARR in inhibiting the growth of cancer stem cells, we examined the inhibition of sphere formation in CD44+/CD24+/EpCAM+ and CD133+ cancer stem cells." (PMID 22570653, 2012). "The epithelial cell adhesion molecule (EpCAM; CD326) is membranous 38-kDa glycoprotein which is highly expressed in cancer tissue of different entities and to a lower extent by normal epithelium." (PMID 22590529, 2012). "Although the roles of EpCAM and TROP2 are not yet fully understood, both proteins are thought to participate in growth and proliferation of carcinoma cells." (PMID 22482828, 2012). "Our CTC detection method is based on a commercially available Carcinoma Cell Enrichment and Detection Kit which uses CK7/CK8 MicroBeads supplemented by EpCAM-MicroBeads." (PMID 22646670, 2012). "It has become axiomatic in the field that all CK and/or EPCAM positive, CD45-negative cells with a nucleus in cancer patients are CTCs." (PMID 21577258, 2011). "By defining CTCs in carcinoma patients as CD45-CK+ and/or EpCAM+, the detection rate increased to 73% (61/84)." (PMID 21595914, 2011). "The epithelial cell adhesion molecule (EpCAM; CD326) is a transmembrane glycoprotein, highly overexpressed on most carcinomas." (PMID 21694727, 2011). "The human-engineered and humanized anti-EpCAM antibodies ING-1 and 3622W94, respectively, were developed and tested in clinical phase 1 studies in cancer patients." (PMID 21044305, 2010). "In addition, based on our findings that EpCAM may be weakly expressed in certain subtypes of cancer, current technologies that limit capture to using EpCAM alone could significantly benefit from adding markers of mesenchymal phenotype to improve CTC counts and prevalence in patients." (PMID 20838621, 2010). "Occurrence of EpCAM+ DTC in lymph nodes and in peripheral blood samples of cancer patients has also been shown to correlate with poor survival." (PMID 17211480, 2007).
cancer (continued). "Furthermore, we found that EpCAM-positive HCC cells exhibit features of cancer stem cells (CSCs), which are believed to play essential roles in cancer initiation, maintenance, drug resistance, and distant metastasis, as they express high levels of AFP." (PMID 41140754, 2026). "Associated biomarkers of importance for CTC detection include epithelial cell adhesion molecule (EpCAM), human epidermal growth factor receptor 2 (HER2), programmed death ligand-1 (PD-L1), cluster of differentiation 45 (CD45) and other cancer-specific biomolecules." (PMID 41766633, 2026). "Furthermore, our study demonstrates that circ_0000467 promotes cancer stem cell (CSC) characteristics, as evidenced by increased spheroid formation and elevated levels of CSC markers (CD24, CD44, EpCAM, SOX2, and Nanog)." (PMID 40290725, 2025). "RT-PCR analysis showed significantly (p<0.01) higher expression of prominent stem cell factors—SOX2, OCT4, and NANOG—in CD133+EpCAM+ cells compared to their negative fractions, corroborating their characterization as cancer stem-like cells." (PMID 40677705, 2025). "In addition to its usual feature as cancer stem cell (CSCs) or CTC biomarker, the EpCAM is a relevant object of CTC capture and targeted therapy." (PMID 40076201, 2025). "EpCAM-positive CSCs self-renew and differentiate into EpCAM-positive and CD90-positive cancer cells; however, the transcription factors and signaling pathways involved in the plasticity of these CSCs remain unknown." (PMID 40253402, 2025). "Epithelial cell adhesion molecule (EpCAM), which is often found in cancer‐derived EVs, was also not apparent in the EVs." (PMID 39790178, 2025). "Five fully human anti-EpCAM sdAbs were isolated, all of which specifically bound to the EpCAM peptide and showed selective binding to various cancer cell lines, but not to 293T and 3T3 cells." (PMID 40017594, 2025). "Moreover, its expression is not limited to cancer cells, as it is also found in normal epithelial tissues, particularly in the gastrointestinal tract, which may restrict the therapeutic applicability of EpCAM-targeted therapies and raise concerns about potential off-target effects." (PMID 40759634, 2025). "Recently, the selective detection and killing of αCD44, chondroitin sulfate proteoglycan‐4 (CSPG4), epithelial cell adhesion molecule (EPCAM), and EGFR‐expressing TNBC cancer cells using recombinant scFv‐SNAP‐tag‐based fusion proteins conjugated to IR700 dye was reported." (PMID 40970572, 2025). "Taken together, these in silico analyses may provide guidance for further research on the regulatory mechanisms of EpCAM and MGST1 in cancers." (PMID 40778224, 2025). "Our results confirmed that EpCAM-ReTARGTPR effectively engaged CMV-specific CD8pos T cells to eliminate EpCAMpos cancer cells with potency comparable to solitomab, without inducing excessive cytokine release." (PMID 40243928, 2025). "Besides, by evaluating the expression levels of cancer stem cell (CSC) surface markers, EpCAM, CD24, CD133 and CD44 by flow cytometry, we confirmed a direct correlation between stemness markers levels and PHGDH expression in HCT8 and RKO P1 colonspheres." (PMID 40640948, 2025). "EpCAM-ReTARGTPR, EpCAM-ReTARGTPRvIL2, and EpCAM-ReTARGTPRIFNαR149A selectively bound to EpCAM-expressing PC3M cancer cells with no detectable binding to PC3M.EpCAM-KO cells." (PMID 40243928, 2025). "EpCAM was highly expressed in six different cancer cells, while it was not expressed in the normal pancreatic ductal cell line, hTERT–HPNE." (PMID 41417221, 2025). "Advances in EpCAM-targeting strategies, such as monoclonal antibodies, chimeric antigen receptor (CAR) T/NK cell therapies, and aptamer-based systems hold promise for personalized cancer therapies." (PMID 39996844, 2025).